ERBB2 (erb-b2 receptor tyrosine kinase 2)
Diseases named in the same sentence as ERBB2 in open-access papers (continued):
Sharing a sentence is not in itself a finding about the gene and the disease.
breast cancer (continued). "Although TOM1L1 regulates the oncoprotein ERBB2-driven cell invasion with metastatic phenotypes in breast cancer, there is no available information on the role of this gene in CC." (PMID 33023042, 2020). "Further data establish that Cyclin D1 is important for the development of mammary cancers induced by different oncoproteins such as receptor tyrosine-protein kinase erbB-2 (Her2/neu) and v-Ha-ras, but not those induced by c-Myc or Wnt-1." (PMID 33317149, 2020). "By contrast, ERBB2, a breast cancer marker that should not be highly expressed in these clinically ERBB2- (no ERBB2 amplification) cases showed more uniform expression across the different PDX models." (PMID 31988290, 2020). "For example, neratinib (alone or in combination with fulvestrant) was tested in phase II study for patients with advanced, ERBB2 non-amplified, ERBB2mut breast cancer (clinical trial registration number NCT01670877)." (PMID 32782013, 2020). "Altogether, these data indicate that high inclusion levels of ECT2-Ex5 are a predictive marker of bad prognosis in breast cancer, specifically in the HR+ERBB2- subtype (as opposed to triple-negative tumors) and in patients that were treated with chemotherapy." (PMID 31943118, 2020). "We found in this study that trastuzumab upregulates a set of proteins in EVs emitted by trastuzumab-sensitive but not by trastuzumab-resistant ErbB2-positive breast cancer cells in culture." (PMID 33023655, 2020). "Here, the TCGA breast cancer (BRCA) report is selected and the gene query is ERBB2 (HER2)." (PMID 31729402, 2019). "For example, ERBB2 amplification and fibroblast growth factor receptor 1 gene (FGFR1) amplification are drivers of therapeutic resistance and poor prognosis in ER+ breast cancer." (PMID 31106278, 2019). "Finally, cell lines close to the breast cancer-specific HER2 archetype (tumors that over-expresses the erbB-2 receptor) are sensitive to herceptin, an erbB-2 inhibitor." (PMID 31780652, 2019). "The overexpression of ErbB2, a receptor-like tyrosine kinase oncogene also known as human epidermal growth factor receptor 2 (HER-2), influences several signaling pathways and promotes dysregulated growth, oncogenesis, metastasis, and chemoresistance in breast cancer." (PMID 31514467, 2019). "It seems that amplification of ERBB2 gene in ERBB2-positive feline mammary tumors (FMTs) is not frequently found." (PMID 31301170, 2019). "In contrast, the frequency of ERBB2 gene amplification in pancreatic, lung, and breast cancers was similar or lower compared to non-Asian patients." (PMID 31019892, 2019). "In subsequent experiments, we validated whether CHRNA9 and ERBB2 could form a complex by using nicotine as an agonist for CHRNA9 and investigating downstream signaling in breast cancer cells." (PMID 31311925, 2019). "The estrogen receptor (ER), progesterone receptor (PR), and erb-b2 receptor tyrosine kinase 2 (ERBB2, also known as human epidermal growth factor receptor 2 (HER2)), are representative molecular biomarkers that distinguish breast cancer subtypes, i.e., ER+/HER2−, ER+/HER2+, ER−/HER2+, and ER−/HER2−." (PMID 31779659, 2019). "Breast cancers are classified into four subtypes, i.e., luminal A, luminal B, HER2/ErbB2+ (human epidermal growth factor receptor 2/the erythroblastosis oncogene-B2 positive), and TNBC (triple negative breast cancer), based on estrogen receptor (ER), progesterone receptor (PR), and HER2 expression." (PMID 31060224, 2019). "This was not the case however, as flow cytometry of the U87 mg in 2D vs. 3D, dispersed vs. aggregated, yielded no change in ErbB2 expression relative to an isotype negative control, and did not approach the signal of ErbB2+ MCF7 breast cancer cells." (PMID 30926929, 2019). "Lapatinib, known as a small-molecule kinase inhibitor, could target the EGFR gene and Erb-B2 Receptor Tyrosine Kinase 2 (ERBB2) gene, which was approved by the US Food and Drug Administration (FDA) in 2007 for the therapy of breast cancer patients." (PMID 31265947, 2019).
breast cancer (continued). "New potential prognostic biomarkers of breast cancer metastasis are continuously being uncovered, which include uPA/PAI1, ER, PR, HER2/ErbB2, circulating tumor cells, the presence of epithelial cells in the bone marrow, E-cadherin and, more recently, nucleobindin-2." (PMID 31443698, 2019). "Although, PIK3CA is not found in treatment guidelines for breast cancer, as is the case for ERBB2, ESR1 or PGR, it is an oncogene found downstream ERBB2." (PMID 31169290, 2019). "(b) Scatter plot showing a lack of correlation between ITGA3 and ERBB2 expression in CCLE breast cancer panel (Spearman’s rho − 0.17, P = 0.22, n = 51)." (PMID 31101121, 2019). "In agreement with our expression data, functional studies revealed exogenous expression of ERBB2 in ERBB2-negative breast cancer cells (MCF7 and T47D) to enhance the expression of FOXM1 and MMP2." (PMID 31620367, 2019). "Importantly, the differential expression of the selected proteins reflects key clinical parameters defining breast cancer subtypes: ER status (INPP4B); tumor grade (CDK1); and HER2 status (ERBB2)." (PMID 31315058, 2019). "In contrast, pathway models trained with CCLE data successfully identified a few top pathways involving both ERBB2 and EGFR, including “anti-apoptotic action of ErbB2 in breast cancer”, “ERBB family signaling”, “mitogenic action of ErbB2 in breast cancer” and “EGFR signalling via small GTPase”." (PMID 30704449, 2019). "MTT assay was performed to determine the effect of STARD10, ERBB2 and ethanol on cell proliferation, which revealed that STARD10 overexpression enhanced the viability of the mammary tumor cells compared to control in a manner similar to ethanol administration and ERBB2 overexpression." (PMID 30611309, 2019). "In normal breast tissues, STARD10 expression was not detectable at protein level, while in ERBB2 positive human breast cancer tissue, it was expressed in 30% of samples." (PMID 30611309, 2019). "These microarray signatures lead to the stratification of breast cancer patients based on their level of expression of estrogen receptor alpha (ERα), progesterone receptor (PR), or the human epidermal growth factor receptor 2; ERBB2 (HER2)." (PMID 31817827, 2019). "In this study, MS-lincRNA BCLIN25, which serves as a HER2 subtype-specific lincRNA, was found to contribute to tumorigenesis by upregulating ERBB2 expression via epigenetic modification and RNA–RNA interactions in breast cancer." (PMID 31801944, 2019). "Our data also revealed upregulation of not only ERBB2, but also ERBB3 and ERBB4 in breast cancer." (PMID 31620367, 2019). "Based on our result, regardless of ErbB-2 or Met took charge, Plexin-B1 was an independent prognosis marker for breast cancer patients." (PMID 30762724, 2019). "LOH towards the mutant allele occurred in ERBB2 and BRCA2 only in the patient metastases of CM01 (including the primary breast cancer), CM02, CM03, and CM08 but not in their corresponding PDCs." (PMID 30700832, 2019). "RET genomic alterations were detected across all breast cancer subtypes although a majority were ER− (65%) or ERBB2 nonamplified (82%)." (PMID 30446652, 2018). "BRCA1 and ERBB2 splicing, as well as splicing of BCL-X and MCL-1 are examples of common driver oncogenes and tumour suppressor genes that can be aberrantly spliced in breast cancer." (PMID 29848666, 2018). "This retrospective biomarker analysis included 774 postmenopausal women with ER-positive ERBB2 (formerly HER2)–negative breast cancer." (PMID 29450494, 2018). "The contribution of these let-7 targets to the invasion of ErbB2-positive breast cancer cells has not been addressed." (PMID 29396433, 2018). "ErbB2, a member of the human epidermal growth factor receptor (HER/EGFR/ERBB) family, has been reported to be closely related to the occurrence and development of breast cancer." (PMID 29482638, 2018).
breast cancer (continued). "Some researchers identified a protective role of PPARγ against palmitate-induced lipotoxicity in ERBB2-positive breast cancer cell lines (BT474 and MDA-MB-361), but not in other types of breast cancer (MCF-7) and normal cells." (PMID 29966227, 2018). "They suggested that ERBB2 has a role in early stages of breast cancer development independent of gene amplification." (PMID 29720211, 2018). "The results presented here link MZF1 and let-7 to lysosomal processes in ErbB2-positive breast cancer cells that in non-cancerous cells have primarily been connected to the transcription factor EB." (PMID 29396433, 2018). "In line with that, other breast cancer assays, like the GeneXpert Breast Cancer STRAT4 assay from Cepheid, that also measures the expression levels of ERBB2, ESR1, PGR and MKI67, found that macrodissection of whole tissue sections is not required for accurate assessment of these genes by RT-qPCR." (PMID 30342538, 2018). "Of note, we found that ErbB2-targeted drugs such as trastuzumab upregulate Irf6 in trastuzumab-sensitive but not in trastuzumab-resistant ErbB2-producing detached human breast cancer cells." (PMID 30545388, 2018). "Please note that there are differences in the composition of the cohorts; our dataset does not exactly represent the breast cancer population as seen in daily practice, with an underrepresentation of ERBB2-amplified cases." (PMID 30544876, 2018). "The critical fault of IGF1R inhibitor is the lack of a predictive biomarker such as ERBB2-positive breast cancer for trastuzumab or ALK-fusion protein-driven NSCLC for crizotinib." (PMID 30404198, 2018). "Breast cancer (BC) is a heterogeneous disease, which is subclassified into categories depending on the expression of estrogen and progesterone receptors and the amplification of human epidermal growth factor receptor 2 (HER2/ERBB2)." (PMID 30583472, 2018). "In this study, we present a functional link between let-7 family members and breast cancer cell invasion, by identifying MZF1 as a novel target of let-7 and by connecting let-7 to the invasion-promoting lysosomal distribution of ErbB2-positive breast cancer cells via MZF1." (PMID 29396433, 2018). "What is the comparative performance of prognostic multigene signatures for estimation and risk stratification of overall and late distant recurrence in estrogen receptor–positive ERBB2-negative breast cancer?" (PMID 29450494, 2018). "Molecular and genetic characteristics strongly influence breast cancer prognosis and treatment, with HER2 amplification (human epidermal growth factor receptor 2 [ERBB2]) and hormone receptor (HR; estrogen receptor [ER] and progesterone receptor [PR]) expression being the best examples." (PMID 30327465, 2018). "Around 20% of breast cancers show amplification of HER2/ERBB2/NEU, either with or without the expression of ER-α." (PMID 30213113, 2018). "As an example, targeting therapy of ERBB2, an important regulator of breast cancer, turns out to be not successful because of the co-amplification and over-expression of its neighbor genes." (PMID 29273853, 2018). "In this project, we showed that disruption of the EGFR/ErbB2-dependent signalling by lapatinib and CP-724714, two inhibitors of the receptor tyrosine kinase (RTK), dramatically reduced the amplitude of the SOCE in breast cancer cells." (PMID 29662626, 2018). "Triple-negative (TN; i.e., ER/PR/ERBB2 negative) breast cancers are considered among the most aggressive of breast cancers and have no targeted treatment options." (PMID 29339815, 2018). "In order to find another specific inhibitor of ErbB2 that might have few effects on EGFR, we also tested trastuzumab, a specific antibody against ErbB2 routinely used in the treatment of advanced breast cancers." (PMID 29662626, 2018). "The high expression of FOXO6 was not a marker of poor prognostic in HR- ERBB2+, HR+ ERBB2-, HR+ ERBB2+, lobular, or ductal breast cancer." (PMID 29484124, 2018).
breast cancer (continued). "In addition, we employed the mouse breast cancer cell line TUBO, derived from BALB-neuT mice that overexpresses activated rat ErbB2/neu." (PMID 30402124, 2018). "Meanwhile, miR-1296-5p was significantly down-regulated in human ERBB2-positive breast cancer tissues compared with ERBB2-negative breast cancer tissues." (PMID 29089858, 2017). "Altogether, these results show that the SRCIN1 gene is frequently, but not obligatorily, co-amplified with ERBB2 in breast cancers, arguing for a potential role of SRCIN1 as a determinant of the clinical heterogeneity of ERBB2 tumours." (PMID 28300085, 2017). "In another study using SK-BR-3 human breast cancer cell line and COS7 monkey fibroblasts transiently transfected with ErbB2, curcumin downregulated ErbB2 protein by ubiquitination through chaperone-dependent ubiquitin ligase, carboxyl terminus of HSP70-interacting protein (CHIP)." (PMID 28286519, 2017). "Although it has substantially improved outcomes for patients with ErbB2-positive breast cancer, about 70% of ErbB2-amplified breast cancers do not respond to trastuzumab." (PMID 28881779, 2017). "Therefore, we examined the role of CIP2A in lapatinib-induced anti-cancer effects in ErbB2-overexpressing SKBR3 human breast cancer cells and 78617 cells, which are derived from spontaneous mammary tumors of MMTV-ErbB2 transgenic mice." (PMID 28938602, 2017). "Ten international pathology institutions participated in this study and determined messenger RNA expression levels of ERBB2, ESR1, PGR, and MKI67 in both centrally and locally extracted RNA from formalin-fixed, paraffin-embedded breast cancer specimens with the MammaTyper® test." (PMID 28490348, 2017). "Finally, the overlap between the expression pattern at the FSHβ locus and ERBB2 signaling is supported by the relationship between gonadotropins, estradiol and HER-2 upregulation in breast cancer patients." (PMID 28068351, 2017). "Their results showed that this short-term lapatinib treatment decreased cell proliferation in ductal intraepithelial neoplasia (DIN), ductal hyperplasia without atypia (DH), and invasive erbB-2/Her2+ breast cancer." (PMID 28061785, 2017). "The aim of this study is to establish ERBB2 specific CAR-T cells that could specifically target and induce apoptosis in breast cancer cell line, SKBR3." (PMID 28885562, 2017). "Our method identified not only many known cancer genes such as CCND1, MYC, ERBB2, RB1 and BRCA1 in breast cancer but also many novel protein‐coding genes as well as non‐coding RNAs that may contribute to carcinogenesis." (PMID 28719033, 2017). "Breast cancer cells are also characterized by increased levels of the ER co-activator amplified in breast cancer-1 (AIB-1) oncogene, which was found to be essential for ERBB2-driven oncogenesis in mice." (PMID 29299178, 2017). "In this current, more concise study with a special focus on breast cancer metastases, we only observed a negative association between APOBEC3B and ERBB2 mRNA levels in both the primary tumor and the metastases (data not shown)." (PMID 28141868, 2017). "In addition, network analysis further demonstrates silencing of the ErbB2 pathway involved in epithelial-to-mesenchymal transition (EMT) and glycolysis dependent breast cancer cell migration." (PMID 28467815, 2017). "Repeat biopsy is also recommended at progression in patients with breast cancer and NSCLC to capture targetable genomic changes such as ERBB2 (human epidermal growth factor receptor 2 [HER2]) copy number amplification (CNA) or EGFR and ALK resistance mutations, respectively." (PMID 32913970, 2017). "Since the effects of phenformin on specific breast cancer subtypes have not been fully explored, we used ErbB2-overexpressing breast cancer cell and animal models to test the anti-cancer potential of phenformin." (PMID 28947975, 2017).
breast cancer (continued). "In terms of ErbB2 downstream effectors, mTOR inhibitor, everolimus, is approved in many countries for advanced hormone receptor‐positive, ErbB2‐negative breast cancer in combination with exemestane." (PMID 28781955, 2017). "As ERBB2 is a surface antigen that is overexpressed in breast cancer, a CAR designed to target ERBB2 could be the ideal solution for the treatment of breast cancer." (PMID 28885562, 2017). "About 70% of ErbB2-amplified breast cancers do not respond to trastuzumab (de novo resistance), and the majority of the trastuzumab-responsive cancers progress within 1 year (acquired resistance)." (PMID 28514745, 2017). "Selected from miRNA microarray and confirmed by real-time quantitative PCR (RT-qPCR), miR-1268b was found to be significantly upregulated in drug sensitive and ERBB2 negative tissues, as well as in breast cancer patients with low clinical stage." (PMID 29163776, 2017). "In an effort to understand the mechanisms by which Mek controls ErbB2 expression in detached breast cancer cells we found that selumetinib does not downregulate ErbB2 mRNA in detached MCF-ErbB2 cells." (PMID 29285258, 2017). "The general subtyping of breast cancer in the clinic is based on the expression of three main types of receptor: estrogen receptor (ER), progesterone receptor (PR) and the human epidermal growth factor receptor 2 (HER2, also known as ErbB2)." (PMID 28583138, 2017). "This type of breast cancer is defined by lacking protein expression of progesterone (PR) and estrogen receptors (ER) as well as by low ErbB2 expression." (PMID 29100507, 2017). "In cell culture, IKK inhibition blocks Erb-B2 Receptor Tyrosine Kinase 2 (ERBB2) activation of NF-κB and induces apoptosis in ER negative ERBB2 positive breast cancer cells." (PMID 28536364, 2017). "Although chemopreventative agents targeting the estrogen/estrogen receptor (ER) pathway have been effective for ER+ breast cancers, prevention of hormone receptor-negative breast cancers, such as Her2/erbB-2+ breast cancers, remains a significant issue." (PMID 28061785, 2017). "In contrast ERBB2 amplification and expression seems to be a founding feature of the GU phenotype, even though no separate and distinct “HER2 subtype” of UC analogous the breast cancer “HER2 enriched” have emerged." (PMID 28388586, 2017). "According to the evaluation of estrogen receptor (ER), progesterone receptor (PR) and human epidermal growth factor receptor 2 (HER-2/ERBB2/Neu), breast cancers are routinely divided into hormone receptor positive, HER-2/Neu amplified, and triple-negative breast cancer (TNBC) subtypes." (PMID 28423538, 2017). "Similar results were obtained with an additional human breast cancer cell line named ZR751, which also overexpresses ERBB2, and showed colocalization of cortactin with F-actin and ERBB2 and a peak of CDR formation at 15 min followed by a decrease at 20 min of Tz treatment." (PMID 28947957, 2017). "Thus, enhancement of ERBB2-mediated signal in EGFR1-directed antibody (cetuximab) and IGF1R-mediated signal in anti-erbB2/HER2 (trastuzumab) antibody-treated breast cancer patients confers resistance to the treatment." (PMID 29119846, 2017). "Specifically, MEMO1 was found to control estrogen receptor α (ERα) sub-cellular localization, phosphorylation, and function downstream of ErbB2/ER or IGFIR/ER thereby activating MAPK and PI3K signaling pathways that promoted breast cancer cell migration and/or proliferation." (PMID 28425924, 2017). "Breast cancers with amplification and/or overexpression of ERBB2 (also known as HER2) have a distinct transcriptional and genomic profile, confirming the central role that ERBB2 plays in the pathogenesis of this subtype of breast cancer." (PMID 28810143, 2017). "The HER2/ERBB2/Neu locus, which is a frequent site of amplification in human breast cancers, was not amplified in any models." (PMID 28430642, 2017).